YAP1 (Yes1 associated transcriptional regulator)
Diseases named in the same sentence as YAP1 in open-access papers (continued):
Sharing a sentence is not in itself a finding about the gene and the disease.
liposarcoma (5 papers, 2016 to 2025). A usually painless malignant tumor that arises from adipose tissue. "Considering the potential interaction among PDGFRβ, SMAD4, and YAP1 in precipitating cancer development, inhibiting these targets by miR-193b can therefore help halt liposarcoma progression." (PMID 39736850, 2025). "To translate our findings in genetically engineered SCP‐1 cells to the setting of endogenous FUS‐DDIT3 expression, we first determined YAP1 mRNA and protein levels in a panel of human liposarcoma cell lines using quantitative RT–PCR and immunoblotting." (PMID 30898787, 2019). "Immunohistochemistry analysis of MLS patient specimens revealed that nuclear YAP1 expression is significantly more prevalent in MLS compared to other liposarcoma subtypes." (PMID 30898787, 2019). "To confirm the differential requirement for YAP1 identified by RNAi screen, we suppressed YAP1 expression in seven human liposarcoma cell lines using two different shRNAs." (PMID 30898787, 2019). "At an RNA level, expression of WWTR1 or YAP1 predicts overall survival in undifferentiated pleomorphic sarcoma and dedifferentiated liposarcoma." (PMID 27129148, 2016). "Utilizing TCGA data, RNA levels of WWTR1 and YAP1 were demonstrated to be inversely correlated with overall survival in dedifferentiated liposarcoma and undifferentiated pleomorphic sarcomas." (PMID 27129148, 2016). "To further explore the involvement of YAP1 in MLS development, we examined the expression of nuclear YAP1, corresponding to the transcriptionally active pool, in 223 primary human liposarcoma specimens (MLS, n = 85; WDLS, n = 55; DDLS, n = 74; PLS, n = 9) using IHC." (PMID 30898787, 2019). "miRNA-mediated post-transcriptional regulation of YAP1 may thus contribute to liposarcoma progression." (PMID 30824765, 2019). "To verify the requirement for YAP1 in the context of endogenous FUS‐DDIT3 expression, we analyzed the prevalence and functional relevance of YAP1 in a representative panel of human liposarcoma cell lines and a large cohort of MLS tumor specimens." (PMID 30898787, 2019). "In summary, we demonstrate that miR-193b controls cell growth and differentiation in liposarcoma by targeting multiple key components (PDGFRβ, SMAD4, and YAP1) in several oncogenic signaling pathways." (PMID 30824765, 2019). "YAP1 knockdown depleted FUS‐DDIT3‐expressing MLS 402‐91 and MLS 1765‐92 cells to a similar extent as knockdown of KIF11, an essential cell cycle regulator that served as positive control, whereas there was little effect in cell lines representing other liposarcoma subtypes." (PMID 30898787, 2019). "Expectedly, YAP1 positivity was not restricted to MLS; however, nuclear expression of YAP1 was significantly more prevalent in MLS compared to other liposarcomas, and YAP1‐positive tumors showed strong expression of the YAP1 downstream targets FOXM1 and PLK1." (PMID 30898787, 2019).
liver disease (5 papers, 2020 to 2025). "Altogether, our animal results combined with the scRNA‐seq analysis in human samples suggested that the function of MSCs in suppressing inflammation in liver diseases was dependent on YAP1 expression." (PMID 37544916, 2023). "Accumulating evidence have supported the protective effect of YAP1 in liver disease, nevertheless, a small amount researches involved the YAP1 function in the genesis and development of septic liver injury." (PMID 36182901, 2022). "In the advanced stages of liver disease in rat models, YAP1 expression was higher than in normal liver tissue." (PMID 33763375, 2021). "To further explore whether YAP1 expression in MSCs is correlated with the inflammation status in human liver diseases, we analyzed publicly available scRNA‐seq datasets of human liver diseases." (PMID 37544916, 2023). "Multiple researches recognized YAP1 as an pro-fibrogenic factor, however due to different liver disease models, the role of YAP1 in hepatic anti-fibrosis may be controversial." (PMID 32296329, 2020). "Using publicly available scRNA‐seq data, we observed a negative correlation between YAP1 expression in MSCs and inflammation level of patients with liver disease." (PMID 37544916, 2023).
lymphoma (5 papers, 2020 to 2025). A malignant (clonal) proliferation of B- lymphocytes or T- lymphocytes which involves the lymph nodes, bone marrow and/or extranodal sites. "The expression levels of YAP1 were higher in tumor tissues than in normal control tissues for pancreatic, gastric, colorectal, and brain cancers and lymphoma." (PMID 34150844, 2021).
malignant mesothelioma (5 papers, 2017 to 2022). A malignant neoplasm of the pleura or peritoneum, arising from mesothelial cells. "Recent studies have associated elevated YAP1 protein activity with a poor prognosis of malignant mesothelioma and its resistance to current therapies, but its role in tumor maintenance is unclear." (PMID 35689194, 2022). "Most malignant mesotheliomas (MPMs) frequently show activated forms of Yes-associated protein 1 (YAP1) and transcriptional co-activator with PDZ-binding motif (TAZ), which transcriptionally regulates the receptor for hyaluronic acid-mediated motility (RHAMM)." (PMID 29212185, 2017). "In this study, we investigate the dependence of malignant mesothelioma on YAP1 signaling to maintain fully established tumors in vivo." (PMID 35689194, 2022). "Specifically, the inhibition of YAP1 activation and the subsequent reduction of already established tumors in vivo clearly demonstrate that YAP1 is a driver of tumor maintenance in malignant mesothelioma with the Hippo pathway or NF2 deletions." (PMID 34685695, 2021). "The inhibition of YAP1 in preclinical models of malignant mesothelioma with Hippo pathway alterations decreased YAP1-dependent gene transcription and inhibited tumor cell growth." (PMID 34685695, 2021). "We have now entered a new phase of investigation, where the safety and relevance of YAP1–TEAD in driving human disease will be tested clinically, in particular for oncology and tumors such as malignant mesotheliomas." (PMID 34685695, 2021).
microphthalmia (5 papers, 2017 to 2023). Congenital or developmental anomaly in which the eyeballs are abnormally small. "We identified a novel 1 bp deletion in YAP1 in a boy with bilateral microphthalmia and bilateral chorioretinal coloboma." (PMID 28801591, 2017). "YAP’s importance in the eye and corneal development was evident as single-copy deletion of the Yap1 gene in mice induced complex ocular abnormalities, including microphthalmia, thinner Descemet’s membrane, and corneal fibrosis, the latter phenotype being reminiscent of LSC deficiency." (PMID 37095157, 2023).
oral cancer (5 papers, 2020 to 2023). "The expression of MT3 in oral cancer cells promotes the expression of YAP1, thereby regulating the stemness of tumor cells." (PMID 38041044, 2023). "YAP1 is an overexpressed and amplified oral cancer oncogene, suggesting a role for RAMP1 in oral cancer promotion." (PMID 37443709, 2023). "It has been reported that YAP1 promotes the stemness and drug resistance of many tumors, and here, we proved that it is highly expressed in chemoresistant oral cancer tissues." (PMID 38041044, 2023). "Nevertheless, this study has proven that the use of YAP1 inhibitors can effectively reverse the chemoresistance of oral cancer, providing suggestions for the current clinical treatment of oral cancer." (PMID 38041044, 2023). "We treated mice inoculated with oral cancer and found that a YAP1 inhibitor can effectively suppress the cisplatin resistance of OSCC tumor cells." (PMID 38041044, 2023). "In animal models, using YAP1 inhibitors improved the effectiveness of cisplatin in treating chemoresistant oral cancer." (PMID 38041044, 2023). "Finally, the therapeutic efficacy of combining a YAP1 inhibitor with cisplatin was confirmed by inoculating an oral cancer cell line in mice." (PMID 38041044, 2023). "We found that MT3 may mediate the chemotherapy resistance of oral cancer through YAP1." (PMID 38041044, 2023). "YAP1/TAZ activation is sufficient to drive carcinogenesis in mouse models of cervical and oral cancer, and the YAP1 inhibitor verteporfin reduced the growth of HPV-positive tumors in a xenograft model." (PMID 35170430, 2022).
renal carcinoma (5 papers, 2017 to 2025). A carcinoma arising from the epithelium of the renal parenchyma or the renal pelvis. "In renal cancer cells, the function of these kinases is often lost, leading to the overactivation of YAP1 and TAZ." (PMID 39859168, 2025). "The present results confirmed the anticancer role of Eupatilin in vitro and in vivo by showing that Eupatilin suppressed renal cancer cell growth by modulating miR-21 and YAP1 expression." (PMID 31179326, 2019). "The present study is the first to demonstrate that Eupatilin exerts proapoptotic and antimigratory effects on renal cancer cells via the miR-21/YAP1 signaling axis." (PMID 31179326, 2019). "Eupatilin downregulated miR-21 and suppressed the expression of YAP1, ultimately leading to cell apoptosis of renal cancer cells." (PMID 31179326, 2019). "In conclusion, Eupatilin inhibited the expression of miR-21, which mediated the proapoptotic and antimigratory effects of Eupatilin by suppressing YAP1 in renal cancer cells." (PMID 31179326, 2019). "To confirm that YAP1 was involved in the effect of miR-21 on promoting renal cancer cell growth, we investigated whether exogenous expression of YAP1 affected the phosphorylation of AKT and the effects of miR-21 in 786-O cells." (PMID 31179326, 2019). "Eupatilin inhibited the expression of miR-21 via YAP1-AKT pathway in renal cancer cells." (PMID 31179326, 2019).
schwannoma (5 papers, 2022 to 2025). A benign, usually encapsulated slow growing tumor composed of Schwann cells. "In such patients, the identification of a somatic non-NF2 driver alteration such as this newly described YAP1 fusion, can help ascertain the diagnosis of a sporadic schwannoma." (PMID 35986430, 2022).
uveal melanoma (5 papers, 2018 to 2022). A melanoma derived from melanocytes of the uveal tract. "Recent studies have shown that chloroquine sensitizes GNAQ/11-mutated metastatic uveal melanoma to MEK inhibition via downregulation of YAP1 transcriptional activity." (PMID 35847840, 2022). "PLCB4 is also occasionally mutated in uveal melanoma, suggesting that a positive feedback loop may link YAP1 activation with GPCR signaling in a subset of human malignancies." (PMID 29565815, 2018). "In uveal melanoma, activation of Gαq/11 drives cell proliferation and stimulates the ‘MAPK’ pathway and activates the Hippo pathway through nuclear localization of YAP1 via a TRIO-RHO/RAC signaling circuit." (PMID 34939927, 2021).
adenoma (4 papers, 2016 to 2021). A neoplasm arising from the epithelium. "Of note, parathyroid cells of the rim of normal tissue surrounding adenomas showed intense nuclear YAP1 expression (black arrow)." (PMID 33670622, 2021). "In pediatric ACT, we have not deliberately assessed whether there is a difference in the expression of YAP1 regarding histology (adenoma and carcinoma) due to the difficulty for histological differentiation in pediatric ACT." (PMID 27705928, 2016). "Nuclear Yap1 was not evident in AAH, adenomas, or surrounding normal lung, but nuclear translocation occurred specifically in hypoxic clusters where a Zeb2-to-Zeb1 switch occurs in a Tgf-β1-rich environment." (PMID 29930325, 2018).
adenomyosis (4 papers, 2021 to 2025). The growth of endometrial tissue inside the muscular wall of the uterine corpus. "In a study, it was found that the expression of let-7a is downregulated in adenomyosis, while YAP1 and TAZ are upregulated." (PMID 41278208, 2025). "By specifically targeting YAP1, researchers have observed improvements in progesterone resistance and an increase in PR expression, marking a significant advancement in adenomyosis treatment strategies." (PMID 39595579, 2024). "A recent report found that Let-7A level was decreased, while the YAP1 level was increased, in uterine junctional zone SMCs in adenomyosis." (PMID 35887822, 2022). "Therefore, let-7a and the Hippo-YAP1 axis may serve as novel therapeutic targets for adenomyosis." (PMID 41278208, 2025).
asthma (4 papers, 2021 to 2025). "It is important to note that angiomotin‐like 2 and cysteine and glycine‐rich protein 2 (Csrp2) both impede asthma progression by suppressing YAP1 activation and restraining airway smooth muscle cell proliferation." (PMID 40066231, 2025). "The miR‐15b‐5p/YAP1 axis potentially influences asthma development by modulating airway smooth muscle cell growth, migration, inflammatory response, and extracellular matrix deposition." (PMID 40066231, 2025). "It has been reported that miR-375 mitigates the ability of airway smooth muscle cells and exerts its antiangiogenic effects by targeting YAP1 in asthma." (PMID 35980290, 2022). "As reported, the dysregulation of YAP1 is pertinent to the pathogenesis of asthma." (PMID 35172671, 2022). "The FERM domain containing 6 (FRMD6)/Hippo/YAP1 pathway may be involved in asthma pathogenesis." (PMID 40066231, 2025). "Importantly, YAP1 is also an important modulator of asthma pathogenesis." (PMID 35172671, 2022). "In conclusion, miR-15b-5p/YAP1 axis modulates the growth, migration, inflammatory response, and ECM deposition of ASM cells, thus participating in the pathogenesis of asthma." (PMID 35172671, 2022). "One of the important findings of the current study is that the factors YAP1 and HIF-1α were both increased in pediatric asthma." (PMID 33980319, 2021).
astrocytoma (4 papers, 2012 to 2025). "Among these identified proteins, the Yap1 transcription factor is known to be implicated in astrocytic proliferation and is known to promote astrocytoma." (PMID 37015912, 2023). "In multivariate analysis, after adjusting for IDH1 mutation, tumour grade, gender and age, YAP1 levels were an independent prognostic factor for chemotherapy-treated recurrent astrocytoma (HR (95% CI): 4.06 (1.32–12.27), p = 0.013)." (PMID 34771529, 2021). "Thus, there may be an association between codon 273 mutant astrocytoma and post-chemotherapy YAP1 levels." (PMID 34771529, 2021). "Our data suggest that YAP1 should be further investigated as a potential druggable target in the sub-group of recurrent chemotherapy-treated MGMT unmethylated astrocytoma." (PMID 34771529, 2021). "We further observed the potential role of MGMT methylation in this study as YAP1 mRNA expression and codon 273 mutation were particularly prognostic in the MGMT unmethylated sub-group of astrocytoma patients treated with chemotherapy." (PMID 34771529, 2021). "Supporting these findings, we found that YAP1 expression was an independent prognostic factor in the chemotherapy-treated group of astrocytoma only." (PMID 34771529, 2021). "Investigating recurrent astrocytoma samples that were specifically treated with chemotherapy was necessary to understand the role of chemotherapy on YAP1." (PMID 34771529, 2021). "Furthermore, we identified sub-groups (codon 273 mutant and/or low YAP1 level) of MGMT unmethylated recurrent chemotherapy-treated astrocytoma that responded well to chemotherapy." (PMID 34771529, 2021). "We next investigated the prognostic role of YAP1 levels in primary and recurrent astrocytoma with and without chemotherapy." (PMID 34771529, 2021). "Indeed, analysis of the TCGA-GBMLGG dataset showed that both IDHmut-codeleted (oligodendrogliomas) and IDHmut-noncodeleted (astrocytomas) have higher WWTR1 and YAP1 DNA methylation, and lower WWTR1 and YAP1 gene expression, compared with IDHwt GBM." (PMID 41066183, 2025).
bladder (4 papers, 2019 to 2025). "In addition, YAP1 expression is not positively correlated with TEAD4, supporting a YAP1-independent function of TEAD4 in prostate carcinogenesis." (PMID 33893278, 2021).
Breast Invasive Carcinoma (4 papers, 2020 to 2022). "To get the gene expression pattern correlated with YAP1 across the patients in Breast Invasive Carcinoma (TCGA, PanCancer Atlas) cohort, we used cBioprtal Co‐expression tool." (PMID 34196131, 2022). "To evaluate the expression pattern of YAP1 in patients with invasive breast cancer (IBC), we collected clinical specimens from six normal and benign breast disease tissues, 21 primary tumors, six positive lymph nodes, and nine distant metastatic lesions." (PMID 35773411, 2022). "We aimed to explore the effect of YAP1 in tumor aggressiveness and immune evasion in breast invasive carcinoma and metastatic breast cancer in the context of Interleukin‐18 (IL‐18) in silico." (PMID 34196131, 2022). "We found 0.3% amplification, 1% deep deletion of YAP1 in Breast Invasive Carcinoma (TCGA, PanCancer Atlas cohort) especially, breast invasive mixed mucinious carcinoma subtype." (PMID 34196131, 2022). "Taken together, the present data provide crucial clinically significant information that IL‐18 expression might become an important prognostic feature in YAP1 overexpressed breast invasive carcinoma and can be considered as a potential target for tumor treatment." (PMID 34196131, 2022). "Our finding also exhibited a positive correlation between IL‐18 and YAP1 via IFNG gene expression and showed that IL‐18 expression is positively correlated with YAP1 in breast invasive carcinoma." (PMID 34196131, 2022). "In conclusion, the present data analysis suggests that IL‐18 might influence YAP1 in Breast oncogenesis through the production of IFNG and IL‐18 expression is positively correlated with YAP1 expression in breast invasive carcinoma." (PMID 34196131, 2022). "In addition, the overall oncoprint of YAP1, IL‐18 and IFNG gene expressions in Breast Invasive Carcinoma (PanCancer Atlas) cohort showed that mRNA expression was up‐regulated by 3.02, 2.82, and 3.22% (YAP1, IL18 and IFNG) in all patients, respectively." (PMID 34196131, 2022).
cardiomyopathy (4 papers, 2022 to 2025). A disease of the heart muscle or myocardium proper. "Thus, the involvement of Hippo and YAP1 in cardiomyopathies is unclear and likely mutation- and tissue-specific, warranting further investigation." (PMID 38539233, 2024). "In conclusion, we generated a unique zebrafish animal model of TNNI3K splicing mutation-based cardiomyopathy and CCD and identified the focal adhesion pathway and Mypt1/Mlc2/Yap1/Nfatc1 axis as the downstream phosphorylation targets of the Tnni3k protein." (PMID 39926332, 2025). "Besides its regulatory role on YAP1/WWTR1, non-canonical functions of MST1 have been connected to mechanisms that are impaired in cardiomyopathies." (PMID 38539233, 2024).